BMAL1 (basic helix-loop-helix ARNT like 1)
Diseases named in the same sentence as BMAL1 in open-access papers (continued):
Sharing a sentence is not in itself a finding about the gene and the disease.
myocardial infarction (10 papers, 2018 to 2026). Gross necrosis of the myocardium, as a result of interruption of the blood supply to the area, as in coronary thrombosis. "Correlation studies of genotype–phenotype interactions have also shown that BMAL1 genetic mutations are associated with circadian rhythm phenotypes in patients with myocardial infarction." (PMID 40429770, 2025). "Genetic polymorphisms in BMAL1 are possible risk factors for myocardial infarction." (PMID 40429770, 2025). "After myocardial infarction, the expression of the BMAL1 is disordered, and the circadian oscillation of neutrophils is destroyed." (PMID 40429770, 2025). "In the pathogenesis of acute myocardial infarction, BMAL1 boosts antioxidant activity by enhancing the redox state of HSPB139." (PMID 38245621, 2024). "Oxidative stress is the main cause of acute myocardial infarction (AMI), which is related to the disorder of the regulation of Bmal1 on the redox state." (PMID 34239687, 2021). "BMAL1 may ameliorate the adverse consequences of myocardial infarction by affecting the aging and cardiac remodeling processes of neutrophils." (PMID 40429770, 2025). "BMAL1 may regulate myocardial fatty acid metabolism and reduce the myocardial infarction area by regulating PER2 gene expression." (PMID 40429770, 2025). "The molecular mechanism is closely related to Histone Deacetylase 3 (HDAC3), a crucial element of the circadian negative feedback loop, which upregulates BMAL1 to restore mitochondrial autophagy by regulating the REV-ERBα/BMAL1 pathway, thereby alleviating myocardial infarction injury." (PMID 40429770, 2025). "In addition, BMAL1 may influence the cardiac remodeling and repair process after myocardial infarction by regulating inflammatory mediators." (PMID 40429770, 2025). "In addition, restoration of BMAL1 circadian rhythm under pharmacological intervention attenuates cardiac fibrosis in myocardial infarction mice by restraining the AKT Serine/Threonine Kinase (AKT) signaling pathway and attenuating cardiac fibroblast proliferation and collagen production." (PMID 40429770, 2025). "The inhibition of SCN function could improve the inflammatory response after myocardial infarction and promote cardiac repair by upregulating BMAL1 to promote insulin-like growth factor 2 (Igf2) expression and inducing macrophage conversion to an anti-inflammatory phenotype." (PMID 40429770, 2025). "The downregulation of the biological clock gene BMAL1/CLOCK leads to circadian rhythm disruption and significant elevation of the pro-inflammatory cytokines CCL2, Interleukin-1 Beta( IL-1β), and IL-6 at the site of myocardial infarction in mice fed a high-fat diet, triggering cardiac inflammation." (PMID 40429770, 2025).
Arthritis (9 papers, 2018 to 2024). Inflammation of a joint. "Genetic disruption of Bmal1 within FLS prevents time-of-day-dependent variation of key arthritis effector molecules within inflamed joints." (PMID 38981514, 2024). "The deletion of essential clock gene Bmal1 in FLS reduced susceptibility to collagen-induced arthritis but did not impact symptomatic severity in affected mice." (PMID 38981514, 2024). "Loss of Bmal1 in FLS rendered these resident immune cells more pro-inflammatory in response to challenge, leading to increased paw swelling, localised infiltration of mononuclear cells and enhanced cytokine production in a model of arthritis." (PMID 30612576, 2019). "Since circadian clock genes were reported to be closely related to the pathogenesis of arthritis and excessive expression of Per2 could induce apoptosis, we examined the effect of MTX on expression of Per2, Bmal1, Clock, and Cry1 that were regarded as “core” clock genes." (PMID 29566767, 2018). "In an arthritis model, Bmal1 deletion in fibroblast‐like synoviocytes (FLS) led to increased Cxcl5 expression and neutrophil recruitment into the joints of mice; however, the molecular mechanism that links Bmal1, Cxcl5, and neutrophil recruitment was not determined." (PMID 36624683, 2023).
heart failure (9 papers, 2011 to 2025). Inability of the heart to pump blood at an adequate rate to meet tissue metabolic requirements. "Because the dysregulation of transcription factors has been implicated in heart failure pathogenesis, our observation that the expression levels of metabolic transcription factors are decreased in Bmal1−/− hearts provides insight into the basis for reduced cardiac function in H-Bmal1−/− animals." (PMID 25389966, 2014). "Our research primarily focuses on BMAL1 in cardiomyocytes, given its central role in cardiac dysfunction and post-MI heart failure." (PMID 38464103, 2024). "Collectively, our data show that defects in the function of the Bmal1 gene in heart lead to progressive heart failure, which results in congestion of multiple organs and a short life span." (PMID 25389966, 2014). "Our findings that H-Bmal1−/− mice develop severe, progressive heart failure with age and display a markedly shorter life span, likely due to cardiac decompensation, indicate that Bmal1 gene expression in the heart is an important component that maintains normal cardiac function throughout life." (PMID 25389966, 2014). "Interestingly, studies have also suggested a relationship between NMDAergic (sympathetic) and GABAergic (parasympathetic) to BMAL1 and Period (Per 2), contributing to chronic neuronal overactivation and neuro-inflammation during clock ablation-induced heart failure." (PMID 39727952, 2024). "Mice without cardiac Bmal1 function show a significant decrease in the expression of genes associated with the fatty acid oxidative pathway, the tricarboxylic acid cycle, and the mitochondrial respiratory chain in the heart and develop severe progressive heart failure with age." (PMID 25389966, 2014). "The circadian regulation of Nampt by the repressor E4BP4 downstream of repressive REV-ERBs, mirrored by the transcriptional activating complex of BMAL1:CLOCK also regulating Nampt expression, links the common feature of decreased NAD+ in heart failure to circadian disruption and aging." (PMID 36062878, 2022). "Our data revealed a pattern of down-regulation of several core-clock genes, including Clock and Bmal1, and non-circadian skeletal muscle genes, such as Mef2 and Ttn, responsible for daily muscle maintenance in the gastrocnemius of the SHR during overt heart failure." (PMID 22076133, 2011).
neuroblastoma (9 papers, 2017 to 2025). Neuroblastoma (NB) is the most common solid, extracranial childhood tumor. "For example, in human neuroblastoma, MYC amplification distorts circadian repressors (NR1D1) and circadian activators (RORA and BMAL1) to cause metabolic rewiring that fuels cancer cell growth and promotes poor patient outcomes." (PMID 37262074, 2023). "These two groups of studies showed that MYC suppressed BMAL1 across a wide range of cancers, including osteosarcoma, neuroblastoma, hepatocellular carcinoma, Burkitt’s lymphoma, and T cell acute lymphoblastic leukemia." (PMID 34299381, 2021). "A recent study addressed this question in neuroblastoma cells where amplified N-MYC suppresses BMAL1 expression." (PMID 34299381, 2021). "SR1078 can upregulate and activate RORα, restore the expression and activation of BMAL1, effectively block MYCN-mediated tumor growth, and enhance the sensitivity of neuroblastoma to chemotherapy." (PMID 41425709, 2025). "Turning to other cancers where BMAL1 is suppressed, MYC amplification in neuroblastoma alters BMAL1 mRNA expression through the induction of NR1D1." (PMID 37262074, 2023). "Deregulated expression of MYC or N-MYC disrupts the molecular clock by directly inducing REV-ERBα to dampen expression and oscillation of BMAL1, and both REV-ERBα and BMAL1 have key roles in N-MYC-driven human neuroblastomas." (PMID 35984550, 2022). "Interestingly, addition of lactate to neuroblastoma cells stimulates NPAS2/BMAL1 activity but its release only showed a rhythmicity in response to BMAL1 knockdown in human bone osteosarcoma epithelial cells (U2OS) cells." (PMID 35387328, 2022).
osteoarthritis (9 papers, 2018 to 2025). A noninflammatory degenerative joint disease occurring chiefly in older persons, characterized by degeneration of the articular cartilage, hypertrophy of bone at the margins and changes in the synovial membrane. "For example, a study defined a regulatory mechanism that links the clock gene BMAL-1 in chondrocytes to the maintenance of cartilage homeostasis, and suggests that circadian rhythm disturbance is one of the important risk factors for osteoarthritis." (PMID 33041790, 2020). "In the context of osteoarthritis, studies have shown that the expression of BMAL1 in human chondrocytes decreases as inflammation severity increases." (PMID 40530333, 2025). "Nobiletin and SR8278 can effectively activate the expression of BMAL1 and inhibit the cell proliferation induced by IL-β in osteoarthritis models." (PMID 40530333, 2025). "Previous studies have shown that core clock proteins exist in some human peripheral tissues, and reduced BMAL1 expression was observed in human knees with osteoarthritis." (PMID 35217644, 2022). "Similarly, studies have shown higher levels of BMAL1 protein in synovium from patients with rheumatoid arthritis than in synovium from patients with osteoarthritis." (PMID 30612576, 2019). "The expression levels of BMAL1 and PER1 are normally in antiphase with each other, as demonstrated, for example, in the synovial membrane samples obtained from patients with osteoarthritis, where high BMAL1 expression coexisted with low PER1 expression." (PMID 29534090, 2018). "Chronic circadian rhythm disruption could lead to osteoarthritis-like pathological changes in rat knees, with increased expression of MMP3, MMP13, and ADAMTS4 in knee cartilage and decreased expression of BMAL1." (PMID 39010104, 2024).
Stroke (9 papers, 2016 to 2026). Sudden impairment of blood flow to a part of the brain due to occlusion or rupture of an artery to the brain. "However, BMAL1 deficiency negatively affects the development of B cells, which contributes to the adaptive immune response to stroke, the pathogenesis of stroke, and endogenous protection from stroke injury 44,53." (PMID 38169640, 2024). "The present investigation illustrated that expression levels of genes implicated in circadian rhythms (such as BMAL1 and CRY1) are lower in patients with nighttime strokes." (PMID 41503592, 2026). "Bmal1−/− females in the stroke model had a more severe infarct core, increased astrogliosis, and a larger volume of densely packed microglia in the cortex at day seven after stroke than Bmal1−/− males, but all these differences vanished by day 14 post-stroke." (PMID 41440117, 2025). "In a clinical study of 55 stroke patients, the result showed that core clock gene Bmal1 methylation induced by PM2.5 exposure was negatively associated with the National Institutes of Health Stroke Scale (NIHSS) score." (PMID 36016550, 2022). "Furthermore, Bmal1 deletion appears to have protective effects in some models of neurological disease, such as tau and α-synuclein (αSyn) aggregation, stroke, and spinal cord injury." (PMID 38032732, 2024). "While these vascular factors could be considered to play a modulatory role in stroke outcome in Bmal1-deficient mice, Bmal1-deficiency per se does, according to our results, not affect regression of the infarct core." (PMID 30314381, 2018).
endothelial dysfunction (8 papers, 2011 to 2025). In vascular diseases, endothelial dysfunction is a systemic pathological state of the endothelium (the inner lining of blood vessels) and can be broadly defined as an imbalance between vasodilating and vasoconstricting substances produced by (or acting on) the endothelium. "Mice with either a deficient Bmal1 or mutant Clock exhibited a dysfunctional circadian clock with vascular injury and endothelial dysfunction." (PMID 26348211, 2015). "In mouse models, genetic disruption of the core clock gene Bmal1, global or endothelial-specific knockout, results in impaired angiogenesis, vascular remodeling, endothelial dysfunction, heightened thrombosis risk, and reduced eNOS–Akt signaling, hallmarks of vascular aging." (PMID 41181393, 2025). "Bmal1 regulates anti-inflammatory and antioxidant pathways essential for maintaining vascular tone and preventing endothelial dysfunction." (PMID 41181393, 2025). "Endothelial dysfunction with reduced vascularity is the central pathology of DR vascular disease, which is largely mediated by bone marrow progenitor cells (BMPCs) expressing the Bmal1 gene." (PMID 41243864, 2025). "Clock genes (e.g., BMAL1, CLOCK, PER, CRY) influence metabolic pathways in peripheral tissues; disrupted expression of these genes can trigger inflammation, endothelial dysfunction, and disruption in heart rate." (PMID 40502800, 2025). "The deletion of endothelial BMAL1 orchestrates the progression of microvascular injury, and the absence of Bmal1 in BMPCs further exacerbates endothelial dysfunction due to their inadequate participation in vascular repair." (PMID 41243864, 2025).
liver fibrosis (8 papers, 2022 to 2025). "Reduced Bmal1 expression is associated with elevated serum alanine aminotransferase levels and with progression to liver fibrosis and HCC." (PMID 41465470, 2025). "We established that suppressed hepatic sympathetic nerve activity in HIRI caused by Bmal1 downregulation in the CG resulted in decreased liver fibrosis and inflammatory cytokine levels, including IL-1β and TNF-α." (PMID 37189459, 2023). "For instance, studies have demonstrated that melatonin ameliorates hepatic fibrosis via melatonin receptor 2 (MT2)-mediated upregulation of BMAL1 and antioxidative enzymes." (PMID 41228459, 2025). "The activity of BMAL1 positively correlates with liver fibrosis, and lipid accumulation decreases in Bmal1 KO mice, which likely explains the reduced inflammation and fibrosis in these mice." (PMID 38342927, 2024). "Although a profibrotic role of these proteins was observed in some studies in the context of kidney, lung, and heart disease, Bmal1 and Clock appear to exert a protective role in other studies related to kidney, lung, and liver fibrosis." (PMID 37487638, 2023). "Bmal1 knockdown significantly reduced liver fat reserve, hepatocyte apoptosis, and liver fibrosis, and it increased liver glycogen accumulation." (PMID 37189459, 2023). "In Xu’s study they demonstrated significantly reduced BMAL1 levels in the classic carbon tetrachloride model of liver fibrosis in mice–a standard model for in vivo liver fibrosis." (PMID 34381183, 2022). "In addition, KLF10 expression is significantly reduced in clock-deficient Bmal1 KO mice, suggesting that Bmal1 is an upstream positive regulator of KLF10 during liver fibrosis." (PMID 38279278, 2024). "The Masson Trichrome staining was used to examine the effect of Bmal1 knockdown on liver fibrosis." (PMID 37189459, 2023). "Strategies that restore reduced BMAL1 could be a therapeutic approach in liver fibrosis–a disease with high unmet medical need." (PMID 34381183, 2022).
Miscarriage (8 papers, 2013 to 2025). A pregnancy that ends at a stage in which the fetus is incapable of surviving on its own, defined as the spontaneous loss of a fetus before the 22th week of pregnancy. "Polymorphisms in the circadian clock genes are also associated with a higher risk of miscarriage, and gene variants were found in BMAL1 and NPAS2." (PMID 36675058, 2023). "Brain and muscle ARNT-like protein 1 (BMAL1) is considered as a crucial role in fertility, and polymorphism of BMAL1 gene has been reported to be associated with risk of miscarriage." (PMID 29163762, 2017). "Studies have shown that BMAL1 dysregulation impairs the ability of decidual stromal cells to regulate trophoblast invasion, leading to implantation defects and recurrent miscarriage." (PMID 40772309, 2025). "An analysis of the relationship between the decidual circadian rhythm and recurrent miscarriage showed that BMAL1 expression in the human decidua during early pregnancy was decreased in patients that experienced recurrent miscarriage." (PMID 36675058, 2023). "Endometrial BMAL1 expression levels are lower in human recurrent-miscarriage sufferers." (PMID 36675058, 2023). "In addition, BMAL1 expression was downregulated in recurrent miscarriage patients, and BMAL1 was revealed to affect trophoblast invasion during decidualization by regulating TIMP3, a protein that controls the invasiveness of trophoblast cells." (PMID 35311235, 2022). "BMAL1, a circadian clock gene, is reported crucial for female reproduction especially during embryonic implantation, and shares a potentially close relationship with miscarriage." (PMID 29163762, 2017). "Notably, while both the disturbance of Bmal1 and deficiency of LPA affected miscarriage, a link between the circadian gene Bmal1 and the lipid mediator LPA has been found, suggesting that miscarriage might be the result of lipid disorders caused by circadian clock perturbations." (PMID 39519044, 2024).